VTN (vitronectin)
Diseases named in the same sentence as VTN in open-access papers (continued):
Sharing a sentence is not in itself a finding about the gene and the disease.
pancreatic cancer (3 papers, 2006 to 2025). "Together, these experiments underline the potential of VTN expression as a mitigating factor in the progression of pancreatic cancer." (PMID 40433359, 2025). "Frequent deletion of the VTN locus in pancreatic cancer and its association with advanced disease imply that VTN loss confers a survival advantage by promoting immune evasion." (PMID 40433359, 2025). "For instance, VTN loss in pancreatic cancer may promote stromal fibrosis via dysregulated integrin signaling, fostering an immunosuppressive TME resistant to T-cell infiltration." (PMID 40433359, 2025). "On the other hand, in vivo studies suggest that pancreatic cancer cell lines with upregulated VTN exhibit increased sensitivity to anti-PD1 therapy." (PMID 40433359, 2025). "Further analysis confined to pancreatic cancer substantiated a significant repression in VTN expression in tumor tissues versus normal ones, with a noted downtrend accompanying the progression of the disease, especially marked in stage 4 pancreatic cancer." (PMID 40433359, 2025). "Observations from CCK8 proliferation assays indicated a pronounced reduction in the growth rate of pancreatic cancer cells upon VTN overexpression." (PMID 40433359, 2025). "This study identifies VTN as a dual-functional regulator in pancreatic cancer, acting as both a suppressor of tumor progression and a modulator of immunotherapy response." (PMID 40433359, 2025). "VTN knockdown promoted pancreatic cancer cell proliferation, invasion, and migration in vitro, whereas VTN overexpression suppressed these phenotypes." (PMID 40433359, 2025). "Although the precise mechanisms linking VTN to PD1/PD-L1 require further investigation, our data position VTN as both a prognostic biomarker for immunotherapy response and a therapeutic target to overcome resistance in pancreatic cancer." (PMID 40433359, 2025). "In vitro experiments assessed the impact of VTN knockdown and overexpression on pancreatic cancer cell proliferation, invasion, and migration." (PMID 40433359, 2025). "Our study provides the evidence that VTN acts as a dual regulator of pancreatic cancer progression and anti-PD1 immunotherapy sensitivity." (PMID 40433359, 2025). "This tumor cell-specific localization aligns with our observation that VTN levels are significantly reduced in pancreatic cancer tissues compared to adjacent normal tissues and correlate inversely with disease progression." (PMID 40433359, 2025). "While the precise molecular mechanisms require further exploration, our results tentatively establish VTN as a critical nexus between tumor progression and immune evasion in pancreatic cancer." (PMID 40433359, 2025). "In order to investigate the functions of VTN in pancreatic cancer, single-cell analysis was performed using CancerSEA." (PMID 40433359, 2025). "We analyzed the expression of VTN in pancreatic cancer using single-cell RNA sequencing data from two independent datasets, GSE1627089 and GSE148673." (PMID 40433359, 2025). "On one hand, overexpression of VTN in pancreatic cancer cell lines significantly hinders cellular proliferation, invasion, and migration." (PMID 40433359, 2025). "Our findings reveal that VTN’s antitumor activity in pancreatic cancer is mediated, at least in part, through its multifaceted interactions with immune regulatory factors." (PMID 40433359, 2025). "In closing, this study postulates that VTN constitutes a latent prognostic marker and therapeutic target for pancreatic carcinoma, as well as a predictive and potentiating target for the efficacy of anti-PD1 interventions." (PMID 40433359, 2025). "In the present study, we examined eight pancreatic cancer cell lines for adhesion, proliferation, and migration, on types I and IV collagen, fibronectin, laminin, and vitronectin, as well as integrin expression." (PMID 16622460, 2006).
pancreatic cancer (continued). "Additionally, pancreatic cancer data from Kaplan-Meier Plotter corroborate our findings, showing improved prognosis for patients with high VTN expression and better therapeutic outcomes when treated with anti-PD1 or anti-PD-L1." (PMID 40433359, 2025). "VTN downregulation in pancreatic cancer tissues may disrupt ECM remodeling processes that sustain stromal stiffness." (PMID 40433359, 2025). "VTN was significantly downregulated in pancreatic cancer tissues compared to normal tissues." (PMID 40433359, 2025). "The extracellular matrix protein vitronectin (VTN) has been implicated in tumor progression, but its specific role in pancreatic cancer progression and immunotherapy response remains unclear." (PMID 40433359, 2025). "Moreover, by leveraging a lentivirus to boost VTN expression within the PANC02 pancreatic cancer cell line in mice and subsequently crafting a subcutaneous tumor model, we observed an amplified therapeutic response when coupled with anti-PD1 administration." (PMID 40433359, 2025). "VTN in pancreatic cancer may compete with TGF-β ligands for integrin binding, suppressing EMT and stromal crosstalk, as evidenced by reduced invasion/migration upon VTN overexpression." (PMID 40433359, 2025). "VTN is ubiquitously present in human plasma and the extracellular matrix, our findings suggest that its decline in pancreatic cancer tissues is predominantly driven by intrinsic downregulation within malignant cells rather than systemic depletion in peripheral blood." (PMID 40433359, 2025). "This evidence supports the hypothesis of VTN’s potential anti-cancer properties in the context of pancreatic cancer." (PMID 40433359, 2025). "Adhesion of pancreatic cancer cell lines on vitronectin was the most variable." (PMID 16622460, 2006). "However, our research indicates a paradoxical role for VTN in pancreatic cancer." (PMID 40433359, 2025). "Furthermore, we utilized the TISCH database to further analyze the relationship between VTN and the risk of different cancer types, and the results indicated a negative correlation between VTN expression and the risk of pancreatic cancer." (PMID 40433359, 2025). "We utilized the Human Protein Atlas database to detect the expression of VTN in different pancreatic cancer cell lines, and selected PANC1 with low expression of VTN and PATU8988 with medium expression of VTN for subsequent experiments." (PMID 40433359, 2025). "Pancreatic tumor cells lacking integrin β1 protein had lower tumor forming ability in 3D collagen gels and showed reduced cell adherence and spreading on fibronectin or vitronectin." (PMID 34638957, 2021).
pneumonia (3 papers, 2018 to 2025). An acute, acute and chronic, or chronic inflammation focally or diffusely affecting the lung parenchyma, caused by an infection in one or both of the lungs (by bacteria, viruses, fungi, or mycoplasma.). "Pathogens causing pneumonia utilize the complement regulator vitronectin to evade complement-mediated killing." (PMID 30061873, 2018). "The average pulmonary vitronectin levels presently detected in patients with pneumonia were similar to those reported for subjects with untreated sarcoidosis." (PMID 30061873, 2018). "Taken together, these results indicated that the vitronectin concentrations in BALF samples were significantly higher in patients with clinical pneumonia relative to those in healthy controls." (PMID 30061873, 2018). "We detected increased vitronectin concentrations in lavage fluid during pneumonia (p = 0.0063) and after bronchial endotoxin challenge (p = 0.016)." (PMID 30061873, 2018). "We present several lines of original evidence that vitronectin levels are increased in the bronchoalveolar space during pneumonia due to bacterial surface components including endotoxins that is a major component also in OMV." (PMID 30061873, 2018). "Patients with pneumonia had markedly increased BALF concentrations of vitronectin (median 2.70 μg/ml, range 0.37–88.7 μg/ml) compared with the 13 healthy control subjects (median 0.97 μg/ml, range 0.36–1.34 μg/ml), as revealed by ELISA." (PMID 30061873, 2018). "The concentrations of vitronectin were elevated in BALF samples isolated from patients with pneumonia." (PMID 30061873, 2018). "We present evidence that vitronectin is an “acute phase” protein in the lungs of humans and mice, the levels of which are elevated in the human bronchoalveolar space during clinical pneumonia." (PMID 30061873, 2018). "Five of the pneumonia patients exhibited vitronectin concentrations exceeding this interval, with patient #2 demonstrating strongly elevated levels (88.7 μg/ml)." (PMID 30061873, 2018). "Vitronectin was analyzed in cell-free bronchoalveolar lavage fluid harvested from patients with pneumonia (n = 8) and from healthy volunteers after subsegmental endotoxin instillation (n = 13)." (PMID 30061873, 2018). "Despite the role of vitronectin in the inhibition of complement-mediated killing, regulation of vitronectin release during pneumonia by factors such as bacterial PAMPs remains unknown." (PMID 30061873, 2018). "This study sought to reveal the involvement of vitronectin in the bronchoalveolar space during pneumonia, to assess the effect of outer membrane vesicles and endotoxin on vitronectin release, and to determine whether bacterial pathogens utilize pulmonary vitronectin for evasion." (PMID 30061873, 2018). "The aim of this study was to determine whether vitronectin levels are elevated in the lung during pneumonia, in response to bacterial outer membrane vesicles and endotoxins, and whether pulmonary vitronectin is utilized by the respiratory pathogens to increase fitness." (PMID 30061873, 2018). "Although vitronectin is associated with several chronic lung diseases, the role of bronchoalveolar vitronectin in pneumonia has not been studied." (PMID 30061873, 2018). "BALF samples from pneumonia patients conferred complement resistance to the bacterial cells, whereas vitronectin-depleted BALF samples from the same patients did not." (PMID 30061873, 2018). "To assess whether vitronectin was available at sufficient levels for bacterial binding in the BALF samples and was not quenched or inhibited by other components, we incubated NTHi 3655 and P. aeruginosa KR796 with BALF obtained from pneumonia patients." (PMID 30061873, 2018).
rectal cancer (3 papers, 2015 to 2025). A primary or metastatic malignant neoplasm that affects the rectum. "Since numerous SPINK members also act as inhibitors of serine protease uPA, whether SPINK4 can dissociate the binding between matrix-bound vitronectin and the uPA receptor to create a metastatic niche in rectal cancer needs to be confirmed." (PMID 34202399, 2021). "The biomarker signature was comprised of seven proteins (CADM1, LGALS3BP, HYOU1, FN1, VTN, LRG1, and MRC2) (Fig4A) that could predict the localization of rectal tumors especially well (86% of subjects with rectal cancer)." (PMID 26253080, 2015).
sarcoma (3 papers, 2016 to 2017). A usually aggressive malignant neoplasm of the soft tissue or bone. "Finally, two xeno‐free matrix proteins, vitronectin and human laminin‐521, were compared for their ability to replace Matrigel (a mouse sarcoma extract)." (PMID 28297587, 2017).
Sepsis (3 papers, 2009 to 2025). Sepsis is defined as life-threatening organ dysfunction caused by a dysregulated host response to infection. "Levels of VTN increased in pathological conditions related to acute inflammation such as RA and severe sepsis, where it seems to contribute to organ injury." (PMID 33526813, 2021). "Among these are acute-phase reactants such as platelet factor 4, histidine-rich glycoprotein, vitronectin, fibronectin and lipopolysaccharide-binding protein, which increase in sepsis." (PMID 19958532, 2009).
AA amyloidosis (2 papers, 2022 to 2025). Secondary amyloidosis is a form of amyloidosis, that complicates chronic inflammatory disorders (mainly rheumatoid arthritis) and is characterized by the aggregation and deposition of amyloid fibrils composed of serum amyloid A protein, an acute phase reactant. "Among these co-deposited proteins, the tryptic peptides of VTN showed the same distribution as the Congo red-positive region in all four cases of AA amyloidosis and two cases of ATTR amyloidosis." (PMID 36240260, 2022). "We conclude that the amyloid deposits in the Eurasian stone-curlew with systemic AA amyloidosis are composed by SAA, vitronectin, ApoA-I and ApoA-IV." (PMID 40892784, 2025).
asthma (2 papers, 2014 to 2015). "It is interesting that vitronectin expression is reduced in asthma (and to a lesser extent, in COPD), even though the underlying mechanism is not clear." (PMID 25768308, 2015). "The purposes of this study are to identify possible cellular sources of vitronectin in the respiratory tract and to determine if there is differential expression in individuals with asthma and COPD." (PMID 25768308, 2015). "However, the percent area of vitronectin expression was significantly lower in asthma and COPD subjects (p = 0.0010)." (PMID 25768308, 2015). "The finding will help in determining whether cells in the respiratory track contribute to the accumulation of vitronectin in the airways and whether the abundance of vitronectin is altered in asthma and COPD." (PMID 25768308, 2015). "The cause for the decreased vitronectin expression in asthma is not clear, however, the reduced concentration of vitronectin in the epithelial/submucosal layer of airways may be linked to airway remodeling." (PMID 25768308, 2015). "Whether the level of vitronectin expression is altered in chronic lung diseases such as asthma and chronic obstructive pulmonary disease (COPD) is not known." (PMID 25768308, 2015). "It is also not known whether vitronectin expression is altered in subjects with asthma and COPD." (PMID 25768308, 2015). "Whether there is any beneficial effect in asthma and COPD to have a reduced level of vitronectin expression is difficult to assess without further information." (PMID 25768308, 2015).
astrocytoma (2 papers, 2022 to 2023). "Circulating protein—(a) vitronectin discriminates LGG from HGG (Sn:98%, Sp:91%, CUS: 3, LOE: III), (b) CTLA-4 discriminates LGG from HGG, (cutoff: 220.43 pg/ml, Sn: 82%, Sp: 78%, CUS:3, LOE:III), (c) pre-operative TGF b1 predict astrocytoma (cutoff: 2.52 ng/ml, Sn: 94.9%, Sp: 100%, CUS:3, LOE:VI)." (PMID 37704931, 2023). "They indicated that rat C6 astrocytoma cell line secreted excessive concentrations of extracellular matrix (ECM) proteins like fibronectin (FN) as well as vitronectin (VN), both of which are either nonexistent or secreted in extremely low concentrations in normal astrocytes." (PMID 35419058, 2022).
Coronary Artery Disease (2 papers, 2013 to 2015). "Ekmekci and colleagues showed that plasma vitronectin levels in patients with coronary artery diseases were significantly increased and positively correlated with the extent of diseases." (PMID 24363825, 2013).
coronary atherosclerosis (2 papers, 2012 to 2025). Atherosclerosis of the coronary vasculature. "Vitronectin levels have been shown to correlate with the extent of coronary atherosclerosis, to be higher in patients with acute coronary syndromes and be an independent risk factor for adverse cardiovascular events in patients undergoing percutaneous cardiac interventions." (PMID 41361833, 2025).
endometrial cancer (2 papers, 2015 to 2023). Primary or metastatic malignant neoplasm involving the endometrium (mucous membrane that lines the endometrial cavity). "We now demonstrate, for the first time, that treatment with activin B increases type II endometrial cancer cell migration, invasion and adhesion to vitronectin." (PMID 26384307, 2015). "Given that activin B specifically enhanced endometrial cancer cell adhesion to vitronectin, we next examined its effects on the levels of integrin αvβ3, well known to be a major receptor for vitronectin." (PMID 26384307, 2015). "Increased vitronectin gene expression has been observed (compared with normal endometrial tissue), but only in stage III endometrial cancer, which may provide a link between vitronectin and the increased ability of cancer cells to metastasize and myometrial invasion." (PMID 36982551, 2023).
endothelial dysfunction (2 papers, 2025). In vascular diseases, endothelial dysfunction is a systemic pathological state of the endothelium (the inner lining of blood vessels) and can be broadly defined as an imbalance between vasodilating and vasoconstricting substances produced by (or acting on) the endothelium. "The sustained presence of inflammatory and matrix remodeling signals, exemplified by CypA and Vitronectin, underscores the multifactorial nature of endothelial dysfunction in senescence." (PMID 39976844, 2025). "Our results are consistent with this hypothesis, since A2M could play a role in inhibiting plasmin (inhibiting fibrinolysis), thus contributing to the hypercoagulable state characteristic of the disease, and vitronectin could be related to the increase in fibrosis and endothelial dysfunction." (PMID 40142826, 2025).
Hyperglycemia (2 papers, 2014 to 2024). An increased concentration of glucose in the blood. "Exposure of endothelial cells to hyperglycemia results in increases of the extracellular concentrations of vitronectin, osteopontin, and TS-1: all of which are αVβ3 ligands." (PMID 25389530, 2014).
Hypertension (2 papers, 2023 to 2025). The presence of chronic increased pressure in the systemic arterial system. "The upregulated circulating proteins in PE+ (AMBP, VTN, CLU, F2, PZP, APCS, and HBB) are involved in blood pressure regulation, extracellular matrix dynamics, and immune system function, highlighting the pathogenesis of this hypertensive disorder in the context of inflammation and immune defense." (PMID 40673030, 2025).
Insulin resistance (2 papers, 2019). Increased resistance towards insulin, that is, diminished effectiveness of insulin in reducing blood glucose levels. "A high level of vitronectin (VTN) is responsible for the advancement of NIDDM, but this gene may be associated with insulin resistance." (PMID 30678306, 2019).
ischemia (2 papers, 2012 to 2023). A hypoperfusion of the BLOOD through an organ or tissue caused by a PATHOLOGIC CONSTRICTION or obstruction of its BLOOD VESSELS, or an absence of BLOOD CIRCULATION. "Of these, various proteins have been previously linked to ischemia, including clusterin, vimentin, and vitronectin." (PMID 37175625, 2023).
liver cancer (2 papers, 2006 to 2025). An epithelial or non-epithelial malignant neoplasm that arises from the liver. "Antigenicity, molecular weight, subcellular localization and expression site predictions were used to shortlist liver cancer associated proteins including AMBP, CFB, CDHR5, VTN, APOBR, AFP, SERPINA1 and APOE." (PMID 39752339, 2025). "Our findings confirm that liver cancer recapitulates chronic inflammatory change and suggested to us that vitronectin might play a role in the recruitment and retention of lymphocytes within tumours." (PMID 17088900, 2006).
liver cirrhosis (2 papers, 2014 to 2019). "Liver cirrhosis (LC) is a disease characterized by pathological accumulation and alteration of extracellular matrix (ECM) proteins; the interaction between two such proteins, collagen and vitronectin (VN), is considered to be the key to controlling ECM remodeling in liver cirrhosis." (PMID 30984549, 2019).